LINC02475 (long independently transcribed non-coding RNA 2475)
Synonyms: LVCAT1
Gene: Long non-coding RNA gene on chromosome 4 (44,016,700 to 44,057,242, forward strand). Ensembl gene ENSG00000251350.
Diseases named in the same sentence as LINC02475 in open-access papers:
LINC02475 is named in the same sentence as 2 diseases in open-access papers, as found by Europe PMC text mining. Sharing a sentence is not in itself a finding about the gene and the disease.
LINC02475 shares sentences with these, for which no sentence is quoted: cancer (1 paper); germ cell tumor (1).